FSIP1 (fibrous sheath interacting protein 1)
Synonyms: HSD10; FLJ35989
Tractability: PROTAC: ubiquitination databases record sites on it.
Safety:
Unwanted effects reported when the protein is acted on. In parentheses: how it was acted on, where the effect was seen, and who reports it.
aspirin-intolerant asthma (source: ClinPGx)
Gene: Protein-coding gene on chromosome 15 (39,588,357 to 39,782,858, reverse strand). Ensembl gene ENSG00000150667.
Subcellular location (Human Protein Atlas): Annulus; Flagellar centriole; Nucleoplasm
Genetic constraint (gnomAD): Loss-of-function variants: 31 observed, 30.64 expected, observed/expected ratio (o/e) 1.01, 90% interval 0.76 to 1.37. The upper end of that interval is the gene's LOEUF score, 1.37, which puts it in group 5 of 6, group 1 being the genes least tolerant of losing a copy. Missense variants: 440 observed, 450.84 expected, observed/expected ratio (o/e) 0.98, 90% interval 0.9 to 1.06. Synonymous variants: 141 observed, 155.76 expected, observed/expected ratio (o/e) 0.91, 90% interval 0.79 to 1.04.
Homologues: Orthologues: chimpanzee FSIP1 (98% identical), macaque FSIP1 (92% identical), pig FSIP1 (75% identical), dog FSIP1 (73% identical), rabbit FSIP1 (71% identical), mouse Fsip1 (60% identical), rat Fsip1 (58% identical), tropical clawed frog fsip1 (25% identical).
Diseases named in the same sentence as FSIP1 in open-access papers:
FSIP1 is named in the same sentence as 43 diseases in open-access papers, as found by Europe PMC text mining. Sharing a sentence is not in itself a finding about the gene and the disease. The quoted sentences say what the papers report.
breast carcinoma (10 papers, 2015 to 2024). "The CTA FSIP1 (fibrous sheath interacting protein 1) is expressed in a majority of breast cancer tissues and is associated with poor prognosis." (PMID 36980267, 2023). "However, the exact role of FSIP1 and its underlying mechanisms in breast cancer breast cancer have yet to be reported in detail entirely." (PMID 30814489, 2019). "In addition, there is evidence to support that FSIP1 is a target of steroid receptor coactivator-3, which is an oncogene associated with breast cancer and a coactivator for nuclear receptors, such as ER-α." (PMID 25826084, 2015). "The upregulation of FSIP1 (fibrous sheath interacting protein 1) correlates with poor prognosis in breast cancer and FSIP1 knockout in a mouse model has been found to improve docetaxel sensitivity." (PMID 36980828, 2023). "In breast cancer tissues, it has been found that FSIP1 expression is correlated with HER2 positive and Ki67 expression, and it is associated with poorer postoperative disease-specific survival probability." (PMID 35692888, 2022). "Such as breast cancer, studies found that the expression of FSIP1 was positively correlated with HER2, recurrence, and metastasis but negatively correlated with survival probability." (PMID 35692888, 2022). "Several studies also showed that FSIP1 was overexpressed in various tumor cells, including breast cancer, bladder cancer, non-small-cell lung cancer, and colon cancer." (PMID 35692888, 2022). "We performed MTT, Caspase-Glo 3/7 Assay, Annexin V staining, wound healing and trans-well assays to evaluate cellular apoptosis, proliferation, migration and invasion in FSIP1 knockout and wild-type breast cancer cell lines." (PMID 30814489, 2019). "FSIP1 knockout significantly reduced the levels of MRP1 in breast cancer cells, and MRP1 overexpression in the FSIP1 knockout SKBR3 and MDA-MB-231 cells significantly attenuated docetaxel sensitization and lowered intracellular docetaxel accumulation." (PMID 30814489, 2019). "The tumor regression effect of docetaxel was significantly higher in mice injected with FSIP1 knockout breast cancer cell, indicating that FSIP1 mediates docetaxel resistance." (PMID 30814489, 2019). "Knocking out FSIP1 significantly attenuated cell growth, invasion and migration, as well as augmenting breast cancer cell sensitivity to docetaxel." (PMID 30814489, 2019). "Since the substrate of MRP1 is broad, we tested how FSIP1 affects the sensitivity of another active agent in breast cancer therapy - doxorubicin." (PMID 30814489, 2019). "We found that breast cancer cells and tissues consistently demonstrated elevated FSIP1 expressions, which correlated with poor overall survival." (PMID 30814489, 2019). "FSIP1 protein expression markedly increased in every breast cancer cell line when contrasted to the HMECs." (PMID 30814489, 2019). "We proceeded to evaluate changes in breast cancer cell sensitivity to docetaxel in the presence of altered FSIP1 expression." (PMID 30814489, 2019). "We identified a potential oncogene FSIP1, whose expression is commonly elevated in breast cancer tissues." (PMID 30814489, 2019). "FSIP1 knockout in breast cancer cells significantly increased their sensitivity to docetaxel both in vitro and in vivo." (PMID 30814489, 2019). "Consistent with this, overexpression of FSIP1 was significantly correlated with poor docetaxel response in breast cancer tissues." (PMID 30814489, 2019). "Our study seeks to clarify the role of FSIP1 in breast cancer through analyzing the relationship between FSIP1 expression in cancer tissues and clinical features, tumor recurrence and patient survival." (PMID 30814489, 2019). "FSIP1 is a component of fibrous sheath in sperm flagellum that assembles AKAP4, which was the original X-linked CT antigen detected in breast cancer." (PMID 25826084, 2015).
breast carcinoma (continued). "Strong correlation was observed between FSIP1 expression and human epidermal growth factor receptor 2 (Her-2) or Ki67 expression in breast cancer (p = 0.027 and 0.002, respectively)." (PMID 25826084, 2015). "Serum FSIP1 level in the 112 patients with recurrent or metastatic breast cancer was also much higher than those of the patients with primary breast cancer (7, 713 ± 3, 065 pg/ml vs. 4, 713 ± 3, 065 pg/ml, p = 0.003)." (PMID 25826084, 2015). "We also checked the expression level of FSIP1 in four typical breast cancer cell lines, including MCF-7 (luminal A), BT-474 (luminal B), MD-231 (triple negative), and SK-BR3 (Her-2 over expression)." (PMID 25826084, 2015). "We tested the level of FSIP1 protein in breast cancer cell lines in order to confirm the outcomes of the clinical data." (PMID 25826084, 2015). "The results indicated that FSIP1expression was significantly higher in breast cancer tissues compared to benign tissues, and FSIP1 expression in breast cancer was found to be correlated with a worse post-operative disease-specific survival." (PMID 25826084, 2015). "We observed that FSIP1 was highly expressed in the serum of recurrent and metastatic breast cancer compared to primary breast cancer." (PMID 25826084, 2015). "The aim of this study was to investigate the protein expression of FSIP1 in breast cancer, and to build up the correlation between FSIP1 expression and the clinicopathological features and prognosis of breast cancer." (PMID 25826084, 2015). "Wound fluid and serum samples from female patients with primary breast cancer, recurrent and metastatic breast cancer, and benign tumors were analyzed for FSIP1 expression using ELISA." (PMID 25826084, 2015). "Expression of FSIP1 protein was significantly higher in breast cancer tissues compared to tumor-adjacent tissues (p = 0.001)." (PMID 25826084, 2015). "This suggests that FSIP1 may not only be a prognostic marker of breast cancer but also a potential drug therapy target." (PMID 35692888, 2022). "Due to its little expression in normal tissues, FSIP1 may become a potential drug target for the treatment of HER2-positive breast cancer." (PMID 35692888, 2022). "Recent experiments from our group found that FSIP1 could bind with Her2 and regulate breast cancer growth and invasiveness." (PMID 30814489, 2019). "In addition, we performed mechanistic studies in in vitro and in vivo breast cancer models to further validate the role of FSIP1 in breast cancer progression and docetaxel resistance." (PMID 30814489, 2019). "Additionally, we examined the effects of FSIP1 on docetaxel sensitivity in a nude mice model transplanted with control or FSIP1 knockout breast cancer cells, and also evaluate its role in tumor metastasis." (PMID 30814489, 2019). "Taken together, FSIP1 mediates docetaxel resistance in breast cancer, at least in part, via MRP1." (PMID 30814489, 2019). "Therefore, we sought to establish a correlation between the clinico-pathological features of breast cancer and FSIP1 expression in breast cancer tissues, as well as to validate its role in tumor progression and chemo-resistance." (PMID 30814489, 2019). "In sum, FSIP1 promotes breast carcinogenesis and mediates docetaxel resistance, and may serve as a novel target in the development of breast cancer therapies." (PMID 30814489, 2019). "Interpreted as a whole, these findings strongly allude to the central role that FSIP1 may have in breast cancer carcinogenesis." (PMID 30814489, 2019). "Furthermore, comparative analysis of 6 pairs of tumor and para-tumor tissues revealed that FSIP1 expression levels were notably higher in breast cancer tissues than in the matched surrounding healthy tissues." (PMID 30814489, 2019). "We analyzed FSIP1 expression in the breast cancer and para-tumor tissues by immunohistochemistry." (PMID 30814489, 2019). "Therefore, further study with large sample size is required to clarify the role of FSIP1 in breast cancer." (PMID 25826084, 2015).
breast carcinoma (continued). "In the present study, a cohort of 286 breast cancer samples was assayed for FSIP1 expression." (PMID 25826084, 2015). "However, the expression levels and clinical implications of FSIP1 expression in breast cancer and especially in the serum and wound fluid were still unclear." (PMID 25826084, 2015). "However, serum FSIP1 level was significantly higher in patients with primary breast cancer than in patients with benign cancer (4, 713 ± 3, 065 pg/ml vs. 1, 798 ± 1, 943 pg/ml, p = 0.001)." (PMID 25826084, 2015). "FSIP1 may play an important role in the tumorigenesis and invasion of breast cancer and is a potential biomarker for breast cancer diagnosis or prognosis." (PMID 25826084, 2015). "Similarly, serum level of FSIP1 in patients with PR-positive breast cancer was significantly higher than that in PR-negative cases (5, 357 ± 3, 066 pg/ml vs. 3, 392 ± 2, 638 pg/ml, p < 0.0001)." (PMID 25826084, 2015). "We are now studying the function of FSIP1 in Her-2 positive breast cancers." (PMID 25826084, 2015). "Similarly, serum level of FSIP1 was higher in patients with recurrent and metastatic breast cancer compared to that of primary breast cancer (7, 713 ± 3, 065 vs. 4, 713 ± 3, 065 pg/ml, p = 0.003)." (PMID 25826084, 2015). "A study has found that FSIP1 can promote the proliferation and encroachment of ER+ and HER2+ breast cancer cells." (PMID 38737444, 2024). "For instance, the fibrous sheath interacting protein 1 (FSIP1), a spermatogenesis related testicular antigen, is aberrantly expressed in breast cancer and regulates its growth and invasiveness." (PMID 32373210, 2020). "Studies confirmed that FSIP1 directly binded to HER2 and inhibited the expression of multiple growth factors in HER2-positive breast cancer cells, leading to a decrease in cell proliferation, cell migration, and invasion capabilities and an increase in apoptosis." (PMID 35692888, 2022). "FSIP1 protein was expressed at higher levels in human epidermal growth factor receptor 2 (Her-2) positive breast cancer tissues compared to Her-2 negative tissues (p = 0.029)." (PMID 25826084, 2015).
breast tumors (3 papers, 2015 to 2023). "FSIP1 is a potential target for cancer therapy since its mRNA level is undetectable in most normal tissues and its expression is elevated in breast tumors." (PMID 25826084, 2015). "We found that FSIP1 knockout can sensitive breast tumors to doxorubicin treatment." (PMID 30814489, 2019). "Another fusion of interest, FSIP1::RP11-624L4.1, is present in 240 (22%) of breast tumors analyzed and in 16 normal breast tissues samples, where it is expressed at significantly lower levels in normal tissues." (PMID 37323575, 2023). "In total, 45.45% of the cases showed high FSIP1 expression in breast tumor tissue with no expression in tumor-adjacent tissues (p = 0.001)." (PMID 25826084, 2015).
gastric cancer (2 papers, 2022 to 2024). A primary or metastatic malignant neoplasm involving the stomach. "In conclusion, we further studied the mRNA FSIP1 which was screened in previous studies and is associated with poor prognosis of gastric cancer." (PMID 38737444, 2024). "To elucidate whether FSIP1 is associated with gastric cancer cells metastasis, we compared the migration and invasion abilities between sh-NC and sh-FSIP1 cells." (PMID 38737444, 2024). "FSIP1 may take a role of the occurrence and could be a potential therapeutic target and offer a new insight into the underlying mechanism of gastric cancer." (PMID 38737444, 2024). "Our previous study reported that fiber sheath interaction protein 1 (FSIP1) was closely associated with gastric cancer progression and could construct a prognostic model based on expression levels." (PMID 38737444, 2024). "Fiber sheath interaction protein 1 (FSIP1) plays a crucial role in cancer development and occurrence, but its influence on gastric cancer is still unclear." (PMID 38737444, 2024). "We found that FSIP1 can promote the proliferation, propagation, and migration of gastric cancer cells, and promote the occurrence of EMT by regulating fibroblasts in TME." (PMID 38737444, 2024). "According to the disease-specific survival time of the TCGA dataset, the gastric cancer patients were divided into high and low expression groups according to the expression of FSIP1." (PMID 38737444, 2024). "Downregulation of FSIP1 significantly inhibited the proliferation of gastric cancer cells, which is shown by CCK-8 assay detection and analysis." (PMID 38737444, 2024). "A gastric cancer cell model with FSIP1 mRNA knockdown was constructed by RNA interference." (PMID 38737444, 2024). "This suggests that FSIP1 supported the EMT of gastric cancer cells." (PMID 38737444, 2024). "In order to clarify whether FSIP1 is related to the growth of gastric cancer cells, we compared the proliferation ability of sh-NC and sh-FSIP1 cells by in vitro experiments." (PMID 38737444, 2024). "We found that FSIP1 was mainly expressed on the cell membrane of gastric cancer cells." (PMID 38737444, 2024). "Through previous studies, we established that the immunohistochemical expression level of FSIP1 in gastric cancer tissues was significantly higher than that in adjacent tissues, and the immunohistochemical expression of FSIP1 was associated with poor prognosis of gastric cancer patients." (PMID 38737444, 2024). "Western blotting showed that FSIP1 was generally upregulated in gastric cancer cell lines." (PMID 38737444, 2024). "This study intends to construct FSIP1 silenced gastric cancer cell model by RNA interference technology, explore the influence of FSIP1 on the degree of malignancy of gastric cancer cell in vitro, and further elucidate the molecular mechanism of FSIP1 promoting the development of gastric cancer." (PMID 38737444, 2024). "However, the exact role of FSIP1 in gastric cancer and its underlying mechanism have not been reported." (PMID 38737444, 2024). "In this study, we showed that FSIP1 was related to the TGF-β signaling pathway by GO and KEGG analysis, which indicated that FSIP1 may regulate the development of gastric cancer by mediating or taking part in the TGF-β signaling pathway, but it was not tested in this study." (PMID 38737444, 2024). "In this study, in order to clarify whether FSIP1 is related to gastric cancer cells metastasis, we explored the effect of knockdown of FSIP1 on EMT-related markers, and we found that N-cadherin protein level and vimentin protein level were decreased in sh-FSIP1 cells." (PMID 38737444, 2024).
triple-negative breast carcinoma (2 papers, 2022 to 2024). An invasive breast carcinoma which is negative for expression of estrogen receptor (ER), progesterone receptor (PR), and human epidermal growth factor receptor 2 (HER2). "FSIP1 silencing inhibited the proliferation, propagation, and migration of triple-negative breast cancer cells (TNBC) in vitro and attenuated the growth of implanted tumors in vivo." (PMID 38737444, 2024). "In addition, FSIP1 positively regulates proliferation and invasion of triple-negative breast cancer (TNBC) cells." (PMID 35692888, 2022).
asthma (1 paper, 2010). "We conducted association study between 66 single nucleotide polymorphisms (SNPs) of the FSIP1 gene and AIA in total of 592 Korean subjects including 163 AIA and 429 aspirin-tolerant asthma (ATA) patients." (PMID 20513247, 2010). "This suggests that FSIP1 might have an effect on aspirin hypersensitivity in asthma, with relation to the nearby potential gene of THBS1." (PMID 20513247, 2010).
bladder cancers (1 paper, 2022). "In the field of tumor biology, FSIP1 is currently recognized as a cancer antigen which is highly expressed in breast, colon, lung, and bladder cancers and associated with poor prognosis." (PMID 35692888, 2022). "This suggests that targeting FSIP1 can be used for further potential therapeutic strategies of bladder cancer." (PMID 35692888, 2022). "In bladder cancer, FSIP1 knockdown inhibited the PI3K/AKT signaling pathway in vitro and in vivo, thereby suppressing the malignant behavior of bladder cancer cells." (PMID 35692888, 2022).
bladder urothelial carcinoma (1 paper, 2024). "And FSIP1 promoted the growth of bladder urothelial carcinoma cells by stimulating the PI3K/AKT signaling pathway, and inhibits tumor cell apoptosis." (PMID 38737444, 2024).
coronary artery disease (1 paper, 2011). "It would be of great interest to investigate gene FSIP1 in determining genetic susceptibility to coronary artery disease." (PMID 21569557, 2011). "However, the LD analysis identifies a well studied gene THBS1 (thrombospondin-1), which is centromeric to gene FSIP1 and has been confirmed to increase the risk of coronary artery disease in many studies." (PMID 21569557, 2011). "We have not found evidence to directly connect gene FSIP1 with the coronary artery disease." (PMID 21569557, 2011).
lung carcinoma (1 paper, 2017). "In this study, we examined the expression and prognostic value of fibrous sheath interacting protein 1 (FSIP1) in 202 non-small cell lung cancer (NSCLC) patients who underwent lung cancer resection at Shengjing Hospital of China Medical University." (PMID 28086239, 2017).
lymph node metastasis (1 paper, 2015). "Spearman correlation analysis revealed strong correlations between lymph node metastasis, Her-2 and Ki67 expression status and FSIP1 expression (p = 0.009, 0.027 and 0.002, respectively)." (PMID 25826084, 2015).
non-small cell lung carcinoma (1 paper, 2017). A group of at least three distinct histological types of lung cancer, including non-small cell squamous cell carcinoma, adenocarcinoma, and large cell carcinoma. "In this study, we measured FSIP1 expression in non-small cell lung cancer (NSCLC) and analyzed the association between FSIP1 and clinicopathological features." (PMID 28086239, 2017).
squamous carcinoma (1 paper, 2017). "In squamous carcinoma, FSIP1 expression was predominantly in tumor cell nucleus and also appearing in the cytoplasm." (PMID 28086239, 2017).